EPO (erythropoietin)
Diseases named in the same sentence as EPO in open-access papers (continued):
Sharing a sentence is not in itself a finding about the gene and the disease.
tumor (continued). "HIF2α behaves as a pro-oncogenic effector in the regulation of erythropoietin, tumor angiogenesis, enhancement of pentose phosphate pathways, resistance to oxidative damage, endoplasmic reticulum stress, and tumor metastasis." (PMID 38233415, 2024). "Drawing inspiration from the erythropoietin (EPO) biosynthetic process, an EPO enhancer is constructed to impart the EPO‐Keap1 plasmid (DNA) with tumor hypoxia‐activated functionality, disrupting the redox homeostasis of the TME." (PMID 38582522, 2024). "EPO can also be inappropriately produced in diseased kidneys (e.g., hydronephrosis or polycystic kidney disease) or by specific tumours." (PMID 36495211, 2023). "In conclusion, in this cohort of HCC patients, a frequent and specific erythrocytosis was evidenced, possibly secondary to EPO secretion by tumor cells related to the antiangiogenic activity of lenvatinib." (PMID 36961524, 2023). "Some of its targets, notably VEGF (Vascular Endothelial Growth Factor), EPO (Erythropoietin) and IGF2 (Insulin Like Growth Factor 2), have been implicated in tumor-induced angiogenesis." (PMID 37542119, 2023). "An EPO-producing tumor was considered; however, contrast-enhanced computed tomography revealed no obvious lesion." (PMID 36890599, 2023). "These genes include VEGF, erythropoietin, lactate dehydrogenase A and glucose transporters, which orchestrate angiogenesis, erythropoiesis, anaerobic metabolism, tumor immune evasion, and other events in the tumor region." (PMID 36998063, 2023). "Immunostaining for EPO in post-treatment surgical specimens demonstrated a strong staining in tumor cells compared to a faint positivity in cirrhotic nodules, suggesting that the tumor was the source of increased EPO production." (PMID 36961524, 2023). "EPO acts on the EPO receptors on the surface of tumor cells to increase the suppression of T cells in the immune microenvironment mediated by macrophages." (PMID 35693827, 2022). "EPO can involve in the development of tumors by promoting tumor angiogenesis and the growth of tumor cells." (PMID 35572724, 2022). "On the one hand, studies in cell culture and animal models have shown that the EPO pathway promotes tumor cell activity, proliferation, metastatic potential, treatment tolerance, and intervention." (PMID 36567722, 2022). "For this reason, utilisation of EPO in cancer patients has been restricted, especially among patients treated with a curative intent and in patients with advanced tumours but long-term survival expectations." (PMID 35626116, 2022). "The Cu-PS, a 5-genes (C7, MAGEA6, HK2, CYP26B1 and EPO) signature, was significantly associated with TNM stage, tumor mutational burden (TMB), drugs sensitivity, and immunotherapies response." (PMID 36250008, 2022). "Concerning its role in tumor angiogenesis, EPO facilitates tumor cell survival, tumor growth, angiogenesis, and lymphangiogenesis through EPOR-dependent and EPOR-independent mechanisms." (PMID 36555679, 2022). "EPO treatment promoted proliferation of both red blood cells and cancer cell lines, leading to shortened survival in mice with grafted tumor cells." (PMID 36518596, 2022). "Increased EPO expression, on the other hand, would suggest increased tumor vigilance, which would be consistent with data in the previous literature." (PMID 36078139, 2022). "Accordingly, treatment outcomes were examined in MP or MPB1 EPO-GEMMs or mice harboring syngeneic subcutaneous or i.p. tumors generated by transplantation of EPO-GEMM–derived tumor cells." (PMID 35082152, 2022). "A recent study found that the application of anti-EPO antibodies to B16 tumor-bearing mice prevented the expansion of the red lineage." (PMID 36567722, 2022).
tumor (continued). "Transcriptomic analyses and mapping of EPO/EPOR target genes are also necessary for tumor and normal cells, on which only signaling and the effect of EPO/EPOR have been described so far, e.g., protective, antiapoptotic, trophic, and other." (PMID 34281163, 2021). "The expression of erythropoietin markers in the tumour cell in CCRCC as well as the involvement of HIF-2 in the carcinogenesis and the efficiency of HIF-2 antagonists in the treatment underscore the importance of identification of the cell of origin." (PMID 34948181, 2021). "HIF-1α is well known as one of the major regulators of the hypoxic response and controls hypoxic expression of erythropoietin, as well as the expression of genes with metabolic functions, which is essential in tumor genesis and inflammation." (PMID 34917160, 2021). "EPO and its receptor have been reported to promote the tumor growth and invasion via an angiogenic effect." (PMID 33816287, 2021). "In tumor tissues, autocrine or paracrine secretion of EPO is typical compared to endocrine distribution of EPO required for erythropoiesis." (PMID 34299300, 2021). "Based upon the occurrence of polycythemia in about 5% of patients with CCRCC we examined renal carcinomas for erythropoietin expression in tumour cells, and found it present in all tumours." (PMID 34948181, 2021). "Ephrin-type B-receptor 4 (EPHB4) was also identified as an alternative EPOR that triggers downstream signaling via STAT3 and promotes recombinant human EPO-induced tumor growth and progression." (PMID 34281163, 2021). "In cancer surgery, the fear occurs to enhance tumour growth via iron supplementation or erythropoietin and re-transfuse circulating tumour cells via cell salvage." (PMID 33523307, 2021). "As the largest family of receptor tyrosine kinases (RTKs), the erythropoietin-producing hepatocellular carcinoma (Eph) receptors are involved in a wide range of physiological activities, especially tumorigenesis, tumor immunity, and tumor angiogenesis." (PMID 33526018, 2021). "This hampers the administration of recombinant erythropoietin in patients with malignant neoplasm, which in this situation can promote tumor cell growth." (PMID 32560029, 2020). "When EPOR signaling was blocked by EPOR knockdown or soluble EPOR against EPO, it inhibited tumor growth and invasion, and resulted in cell apoptosis." (PMID 32015330, 2020). "Otherwise, PDS increased the proportion of both hematopoietic stem cells and erythroid progenitor cells in the bone marrow, but inhibited spleen erythroid differentiation via inhibiting secretion of tumor EPO, GATA-1, and GATA-2." (PMID 32015754, 2020). "Hypoxia-inducible factor 1α (HIF-1α) mediates expressions of VEGF and EPO, important factors that involve tumor angiogenesis." (PMID 30678221, 2019). "Further studies are warranted to better understand functional differences of the multiple forms of erythropoietin on tumor cells." (PMID 30700319, 2019). "The anti-tumor effect of EPO-TAMNLC was sustained, while the effect of TAMNLC was more dose-dependent, with greater effect at higher doses." (PMID 31291309, 2019). "It downregulated the protein expression of HIF-1α and the expression of HIF target genes: vascular endothelial growth factor (VEGF) and erythropoietin, essential for tumor growth." (PMID 31547375, 2019). "In NSCLC, we previously identified high- and low-EPO-R cell population and we found that tumor-derived EPO significantly stimulated the growth of EPO-R-positive NSCLC cells." (PMID 31752873, 2019). "Erythropoietin (EPO) plays an important role in tumor angiogenesis in vivo; it can promote tumor cells survival and growth under hypoxic." (PMID 30678221, 2019). "The enhanced EPO signaling is found within hypoxic tumor regions with highest levels of EPO-R expression." (PMID 31752873, 2019). "It has been shown that EPO acts as a proliferative factor and thereby can promote tumor growth and metastasis." (PMID 31316151, 2019).
tumor (continued). "Based on these observations, we developed the EPO-coated TAM-loaded lipid nanoparticles (EPO-TAMNLC) to enhance the anti-tumor effect of TAM." (PMID 31291309, 2019). "Pathological examination confirmed the production of erythropoietin from the tumor cell as well as the diagnosis of erythropoietin-producing uterine myoma." (PMID 32025892, 2018). "Nevertheless, significant adverse events for EPO treatment have been reported including tumour progression and thromboembolic events." (PMID 30310078, 2018). "In this article we review the angiogenesis potential of EPO on endothelial cells in heart, brain, and leg ischemia, as well as its role in retinopathy protection and tumor promotion." (PMID 28703764, 2017). "Next, we examined mRNA expression of HIF1α, EPO and Cyclin D1 in the tumor tissues from the initial 14 patients whose serum EPO dropped after tumor resections." (PMID 29137269, 2017). "At day 20, the mean tumor size in the group receiving EPO was 37% greater than that in control mice (378 ± 33.9 vs. 238.5 ± 12.1; p < 0.0005)." (PMID 28415825, 2017). "The results showed the pEPOR levels in EPO-elevated tumors (N=14) were significantly higher than those in other tumor specimens (N=21)." (PMID 29137269, 2017). "Erythropoietin (EPO) promotes cancer stem cell self-renewal and expansion in an autocrine/paracrine manner, while blocking EPO signaling inhibits tumor growth both in vitro and in vivo." (PMID 28978182, 2017). "The tumors from the 14 patients whose serum EPO dropped significantly after tumor resections had higher EPO expression compared to the tumors from the other 21 patients." (PMID 29137269, 2017). "As one of the hallmark of tumor, neovascularization is a well-known downstream event of activated HIF-1a through up-regulation of erythropoietin, vascular endothelial growth factor and its receptor." (PMID 28099905, 2017). "In summary, to the best of our knowledge the data presented herein is the first report linking EPO-mediated tumor proliferation to eIF4E activation." (PMID 28415825, 2017). "Secondary erythrocytosis is mainly caused by conditions resulting in increased erythropoietin (EPO) production, including tumor or tissue production." (PMID 28877745, 2017). "The aims of the current study were to examine the effect of EPO on growth and protein synthesis rates in tumor cells and to elucidate the signal transduction pathways involved in these processes." (PMID 28415825, 2017). "Similar observations of reduced tumor growth due to increased drug accumulation were obtained in squamous cell and colon carcinoma xenografts co-treated with 5-Fluoruracil and EPO." (PMID 28703764, 2017). "In general, our study illustrated a subgroup of NSCLC can adapt to tumor microenvironment through EPO signaling." (PMID 29137269, 2017). "Based on current situation, it is quite necessary to conduct further exploration on the effect of EPO, both endogenous and exogenous, on tumor progress." (PMID 29238266, 2017). "Despite the neuroprotective effect of EPO, clinical trials have shown its unexpected side effects, including undesirable proliferative effects such as erythropoiesis and tumor growth." (PMID 28817120, 2017). "The mean score of EPO in tumor tissues was much higher than that in ANLTs, 8.357 ± 0.528 vs 3.679 ± 0.371 (p < 0.001, Wilcoxon signed rank test)." (PMID 29238266, 2017). "Direct intratumoral evidence was first presented in a case of a 64-year-old HCC patient in 2000, of whom tumor expressed higher amount of EPO." (PMID 29238266, 2017). "As expected, treatment of tumor-bearing mice with EPO resulted in a marked increase in hematocrit by the end of the study period when compared to PBS-injected control animals (56.9 ± 1.9% vs. 39.8 ± 1.38%) and to a level comparable to that of naïve mice." (PMID 28415825, 2017). "Phosphorylation of Stat5 and Stat3, which has been reported in various tumor cells following EPO-mediated Jak2 activation was next examined." (PMID 28415825, 2017).
tumor (continued). "We found that EPO therapy significantly accelerated the development of established tumors in C57BL/6 mice as early as 12 days after tumor inoculation and thereafter compared to PBS-treated control mice." (PMID 28415825, 2017). "In this study, the analysis of serum EPO from NSCLC patients and from mouse models supported that EPO was indeed secreted from high EPO-expressing NSCLC tumor cells." (PMID 29137269, 2017). "Compared with HCC15 xenograft mice, the H1819 or H1115 xenograft mice had significantly higher levels of human EPO in serum and in tumor masses." (PMID 29137269, 2017). "In this panel, EPO expression was enhanced in 3/12 tumour samples compared to adjacent normal tissue." (PMID 28623280, 2017). "When all tumors grew up to about 1-cm3 (N=10), human EPO levels in mouse serum and xenograft tumor mass were determined separately by ELISA and western blot." (PMID 29137269, 2017). "The JAK2/STAT5, PI3K/AKT and MEK/ERK signaling pathways are frequently altered in tumor cells and evidence that EPO induces these signal transduction cascades is accumulating." (PMID 28418910, 2017). "We have previously shown that EPO treatment in both 5T2 and 5T33MM mice induced tumor regression and prolonged survival of the 5T33MM mice." (PMID 27481313, 2016). "It was found that in a group of Epo-treated animals, the ratio of recurrence and tumor volume was greater in animals receiving erythropoietin compared with the control group." (PMID 27543111, 2016). "Consistent with the scratch assay, 786-O and Caki-2 cells treated with EPO displayed significant more migratory ability than the control group, resulting in more tumor cells across the Transwell membrane." (PMID 26575329, 2016). "The data here reported confirm that both mitochondrial structure and function are altered in the skeletal muscle of tumor-bearing mice, and that such changes can be rescued by the combined treatment with EPO and exercise." (PMID 26636649, 2015). "This is followed by a more detailed presentation of both pre-clinical and clinical data that demonstrate EPO’s action on cancer cells, as well as tumor angiogenesis and lymphangiogenesis." (PMID 25426117, 2014). "EPO is suspected to be responsible for two major side effects: tumor progression and thromboembolic events." (PMID 25352847, 2014). "As the CT that was performed immediately after the marked increase in EPO level indicated a highly enhanced tumor, and the blood flow of the artery feeding the tumor appeared to have returned." (PMID 25295086, 2014). "Several studies on the use of erythropoietin (Epo) to treat anaemia in patients undergoing cancer treatment have shown adverse effects on tumour control and survival." (PMID 25182342, 2014). "Clear cell renal cancer and positive EPO staining were observed in the cytoplasm of the tumor cells." (PMID 25295086, 2014). "We have previously shown that erythropoietin in combination with surgical trauma stimulates tumour growth." (PMID 25182342, 2014). "The apoptosis-inhibiting effect of erythropoietin can be the common mechanism for the increased tumour survival when it is combined with any treatment – surgery, radiation or chemotherapy." (PMID 25182342, 2014). "In the present work we analyzed the gene expression of EPO and its cognate receptor (EpoR) in a rat model of thioacetamide-induced damage and tumor." (PMID 23052842, 2013). "The proliferative marker, Ki-67, was studied within the tumor sections and an enhanced Ki-67 positivity was noted in EPO-treated 786-O xenograft tumors." (PMID 24004818, 2013). "The transcriptional activity of HIF-1α is activated by hypoxia, thus triggering a series of adaptive responses leading to glucose metabolism, tumor angiogenesis and erythropoietin generation." (PMID 23251251, 2013).
tumor (continued). "A progressive increase of EPO and EpoR mRNA can already be observed during the fibrotic–cirrhotic development with a peak of expression rising at tumor formation (24.7 ± 9.9-fold increase and 15.5 ± 1.1-fold increase, respectively, for the two genes)." (PMID 23052842, 2013). "An understanding of the mechanism of EPO in tumor biology and when EPO treatment is likely to be efficacious is an important goal at this juncture." (PMID 24004818, 2013). "Overproduction of EPO has been described in several tumor conditions among others in the liver, where it has been associated mainly with its angiogenic properties." (PMID 23052842, 2013). "As indicated in the RT-PCR analyses, the expression of EPO mRNA progressively increased up to 24.7 ± 9.9-fold reaching a maximum at week 18 and 16.1 ± 3.5 in the isolated CC (extracted tumor tissue) from 18 weeks TAA-treated livers (*P ≤ 0.05)." (PMID 23052842, 2013). "These investigations provide some insight into the mechanism of EPO in tumor cell stimulus, and show that the effects are significantly enhanced in association with hypoxic conditions." (PMID 24004818, 2013). "We described new tumor cell populations that are able to synthesize EPO in vivo and in vitro, but respond differently to stimulation." (PMID 23052842, 2013). "These in vivo observations confirm the potential of EPO to stimulate cellular proliferation and, hence, tumor growth, especially in a hypoxic setting." (PMID 24004818, 2013). "The present study offers a further insight into the tumor biology of the EPO/EpoR axis, with a particular focus on chronic liver injury and its progression to CC." (PMID 23052842, 2013). "After a two-week administration, the bevacizumab administration significantly attenuated EPO-dependent tumor growth and angiogenesis (P<0.05)." (PMID 22086127, 2012). "The Wilms tumor suppressor (Wt1) can upregulate EPO gene expression, and its colocalization with EPO in developing mice has led to the suggestion that Wt1 contributes to EPO gene regulation in hepatocytes and neuronal cells of the dorsal root ganglia." (PMID 22567318, 2012). "It is particularly worrisome that a large clinical trial evaluating the use of EPO in patients with metastatic breast cancer was recently halted after an increase in mortality within the EPO treatment arm due to tumor progression and/or thrombotic events." (PMID 21766022, 2011). "Erythropoietin (Epo) administration has been reported to have tumor-promoting effects in anemic cancer patients." (PMID 21829709, 2011). "The proportion of patients who experienced tumour progression during the treatment period was similar in both groups (27.0% in the EPO group and 26.1% in the placebo group)." (PMID 21959870, 2011). "If erythropoietin has a direct effect on tumour cell growth, then cancer cells must express functional erythropoietin receptors or protein on their surface." (PMID 18231643, 2008). "Preclinical studies investigating the role of EPO and EPO–EPO receptor signalling on tumour growth and angiogenesis have yielded contradictory results." (PMID 17299396, 2007). "Taken together, these findings are consistent with the dependence of individual tumor cells on early angiogenic activity for both survival and proliferation in vivo and provide evidence for the critical role for endogenous EPO-EPOR in this process." (PMID 17579721, 2007). "Co-injection of erythropoietin with tumor cells or expression of EPOR-R129C in tumor cells significantly stimulated tumor neovascularization and growth in window chambers." (PMID 17579721, 2007). "Co-injection of erythropoietin antagonist proteins (soluble EPOR or anti-EPO antibody) with tumor cells or stable expression of antagonist R103A-EPO protein secreted from tumor cells inhibited angiogenesis and impaired tumor growth." (PMID 17579721, 2007).